MMP28 (matrix metallopeptidase 28)
Diseases named in the same sentence as MMP28 in open-access papers (continued):
Sharing a sentence is not in itself a finding about the gene and the disease.
MMP28 also shares sentences with these, for which no sentence is quoted: acute myocardial infarction (3 papers); fibrosis (2); stable angina (2); adenomyosis (1); atrial fibrillation (1); autoimmune disease (1); bacterial infection (1); colorectal tumor (1); coronary artery disease (1); esophageal cancer (1); glioblastoma (1); heart failure (1); idiopathic pulmonary fibrosis (1); intervertebral disc degeneration (1); malaria (1); musculoskeletal diseases (1); myeloma (1); nasal polyps (1); neurological disease (1); neuropathic pain (1); ovarian carcinoma (1); parasite infections (1); pneumonia (1); pulmonary disease (1); rheumatoid arthritis (1); unstable angina (1); unstable angina pectoris (1); viral infection (1).